S100A7 (S100 calcium binding protein A7)
Diseases named in the same sentence as S100A7 in open-access papers (continued):
Sharing a sentence is not in itself a finding about the gene and the disease.
lung squamous cell carcinoma (6 papers, 2017 to 2024). "Moreover, S100A7 was upregulated in the serum of patients with lung squamous cell carcinoma." (PMID 34323409, 2021). "Desmocollin-3 was the most specific marker for poorly differentiated squamous cell lung carcinoma (100%), followed by CK5/6 (98.3%), glypican-3 (94.8%), Sox2 (94.8%), S100A2 (81%), S100A7 (75.9%), thrombomodulin (72.4%), p63 (48.3%), and HMCK (36.8%)." (PMID 28510121, 2017). "When analyzing only poorly differentiated tumors, HMCK was the most sensitive marker for squamous cell lung carcinoma (100%), followed by p63 (97.8%), CK5/6 (87.0%), Sox2 (71.7%), thrombomodulin (58.7%), desmocollin-3 (52.2%), S100A2 (50%), glypican-3 (45.7%), and S100A7 (45.7%)." (PMID 28510121, 2017). "Our previous study revealed that S100A7 was selectively expressed in lung squamous cell carcinoma tissues but not in adenocarcinoma." (PMID 28177901, 2017).
oral cancer (6 papers, 2010 to 2025). "This test quantitatively measures the S100A7 biomarker in biopsy tissues of patients at risk of oral cancer in conjunction with the StraticyteTM proprietary algorithms, advanced imaging, and digital pathology." (PMID 34359370, 2021). "A study involving a proteomics-based approach identified numerous protein markers, namely prothymosin alpha (PTMA), S100A7, 14-3-3ζ, 14-3-3δ, hnRNPD, and hnRNPK, used for distinguishing between normal mucosa, dysplasia, and oral cancer." (PMID 35741145, 2022). "Further, overexpression of S100A7 inhibited cell proliferation in vitro but promoted tumor differentiation in an orthotopic xenograft oral cancer model, supporting our clinical findings." (PMID 20689826, 2010). "In addition, S100A7 has been identified as a major contributing factor in the occurrence of oral cancer and induces local tumor progression, indicating its role in promoting malignant transformation." (PMID 40560736, 2025). "Patients with overexpression of cytoplasmic S100A7 showed reduced oral cancer-free survival (OCFS) of 68.6 months when compared to patients with weak or no S100A7 expression in immunostaining in the cytoplasm (mean OCFS = 122.8 months)." (PMID 34359370, 2021).
acne (5 papers, 2014 to 2025). An inflammatory process of the sebaceous glands which is characterized by comedones, nodules, papules and/or pustules on the skin. "The overexpression of CCL2 originated from activated TNF signaling pathway and S100A7 with chemotactic activity probably associates with some patients' side effects of “acne-flare” in early stage of isotretinoin treatment." (PMID 32685503, 2020). "Additionally, antimicrobial molecules present in acne lesions, such as hBD-2, S100A7, human neutrophil peptides (HNP) 1-3, and granulin, further enhance the antimicrobial milieu." (PMID 41471878, 2025). "Based on microarray datasets GSE10432, GSE10433, and GSE11792, upregulated expression of LCN2, PTGES, and GDF15 might mediate sebocytes apoptosis; CCL2 and S100A7 could be related with “acne-flare” using isotretinoin for 1 week." (PMID 32685503, 2020). "Suppression of the TNF signaling pathway and S100A7 might be an alternative option for inhibiting “acne-flare” of acne patients while using isotretinoin." (PMID 32685503, 2020). "Using isotretinoin for 1 week, LCN2, PTGES, and GDF15 were upregulated and might mediate sebocytes apoptosis and thus decreased sebum production; CCL2 originated from activated TNF signaling pathway and S100A7 could be related with “acne-flare”." (PMID 32685503, 2020). "In conclusion, this study exhibits that the upregulated expression of LCN2, PTGES, and GDF15 might mediate sebocytes apoptosis and thus decreased sebum production; while CCL2 originated from activated TNF signaling pathway and S100A7 could be related with “acne-flare” using isotretinoin for 1 week." (PMID 32685503, 2020). "AMPs such as hBD-2, LL-37, S100A7, and HNP induced in acne lesions can increase inflammation by recruiting and activating immune cells and releasing pro-inflammatory mediators." (PMID 36235175, 2022). "The expression of AMPs human cathelicidin antimicrobial protein (hCAP18), lipocalin (LCN2), human beta-defensin 2 (hBD2), hBD3, S100A7 and S100A9 were found significantly upregulated in acne lesions in the Finnish patient group by RT-PCR." (PMID 25153527, 2014).
Alzheimer disease (5 papers, 2009 to 2024). A progressive, neurodegenerative disease characterized by loss of function and death of nerve cells in several areas of the brain leading to loss of cognitive function such as memory and language. "Conversely, for hub genes identified from upregulated DEGs, Alzheimer’s disease has been linked to CD2, CDC25A, CKS2, LCK, PRKACG, and S100A7." (PMID 39766348, 2024). "More recently, S100A7 has been identified as a potential biomarker for Alzheimer's disease, with marked increases in both cerebrospinal fluid and brain tissue." (PMID 23285311, 2012). "This study also confirmed the hypothesis that the promotion of S100A7 expression in the brain can selectively promote α-secretase activity in patients with Alzheimer’s disease (AD), preventing the production of amyloidogenic peptides." (PMID 36235175, 2022). "These S100 family members, namely S100A1, S100A6, S100A7, S100A8, S100A9, S100A12, and S100B, seem to be involved in the progression of Alzheimer’s disease (AD), including the formation of amyloid aggregates, and could thereby be promising regarding new therapeutic approaches." (PMID 32722137, 2020).
E. coli infection (5 papers, 2011 to 2023). "Similarly, TERT-NHUC uroepithelial cells cultured under normal glucose condition showed a rapid increase of S100A7 mRNA peaking already after 15 min of E. coli infection." (PMID 36127330, 2022). "As the bactericidal efficiency of S100A7/psoriasin against S. aureus is much lower than against E. coli, these results could indicate that the regular constitutive levels of S100A7/psoriasin expression are sufficient to contain a potential E. coli infection but are inadequate to combat S. aureus." (PMID 21324122, 2011). "Interestingly, Escherichia coli infection is rarely encountered in AD, and the major AMP family that combats this microbe is the S100 proteins, which consist of S100A7 (psoriasin), S100A8, and S100A9." (PMID 29259713, 2017). "Likewise, treatment with the COX-2 inhibitor downregulated the AMP psoriasin, encoded by S100A7, in human uroepithelial cells, 5637 and TERT-NHUC during non-infected state and after E. coli infection on both mRNA and protein levels." (PMID 37697284, 2023).
mastitis (5 papers, 2022 to 2023). Inflammation of breast tissue during lactation or postpartum due to an obstructed duct or infection. "Compared with healthy goat mammary glands, the S100A7 expression was upregulated significantly in clinical mastitis goat mammary glands (p < 0.01)." (PMID 37999476, 2023). "In healthy goats, S100A7 was expressed weakly in the alveolus of the mammary gland of healthy goats while expressed densely in the collapsed alveolus of mastitis goats." (PMID 37999476, 2023). "The study aims to evaluate the relationship between mastitis and antimicrobial peptide S100A7 expression in dairy goats." (PMID 37999476, 2023). "Results showed that the level of S100A7 expression was significantly upregulated in the mammary gland of mastitis dairy goats than in healthy dairy goats." (PMID 37999476, 2023). "The level of S100A7 expression was upregulated in the mammary gland of mastitis dairy goats than in healthy dairy goats." (PMID 37999476, 2023). "With these premises, studying the effects of mastitis on the S100A7 expression in the mammary gland and milk of dairy goats provides a new insight into S100A7’s role in host defenses." (PMID 37999476, 2023). "Furthermore, S100A7 concentration is significantly increased after an intramammary infusion with lipopolysaccharide (LPS); whether the abundance of S100A7 correlates with the degree of inflammation associated with mastitis in goats is still unclear." (PMID 37999476, 2023). "The S100A7 concentration in subclinical mastitis goats was significantly upregulated than in healthy dairy goats (p = 0.0056) and had a limited change with clinical mastitis dairy goats (p = 0.8222)." (PMID 37999476, 2023). "S100A7 is an inflammation-related protein and plays an essential role in host defenses, yet there is little research about the relationship between mastitis and S100A7 expression in dairy goats." (PMID 37999476, 2023). "S100A7 was expressed weakly in the alveolus of a healthy goat mammary gland, while densely in the collapsed alveolus of a mastitis goat mammary gland." (PMID 37999476, 2023). "Based on the bacteriological culture (BC) of goat milk, both estrogen and S100A7 abundance in mastitis samples showed a limited difference compared to healthy samples." (PMID 36428305, 2022). "The average optical density (AOD) of NPR-B and S100A7 in mastitis goat mammary gland was obviously higher than that in healthy goat mammary gland (p < 0.01)." (PMID 35498722, 2022). "The antimicrobial peptide S100A7 plays an important role to resist infection of bacteria in mastitis." (PMID 35498722, 2022). "The expression of CNP, NPR-B, and S100A7 in mammary gland tissue from healthy and mastitis goats was analyzed." (PMID 35498722, 2022). "S100A7 has received extensive attention in the prevention and treatment of mastitis across a broad spectrum, yet there is a little information about its mechanism, especially in the immunomodulatory effects of estrogen." (PMID 36428305, 2022). "The results suggested that the expression of NPR-B and S100A7 was upregulated in mastitis goat mammary gland." (PMID 35498722, 2022). "On the other hand, the expression of NPR-B and S100A7 was upregulated in the mastitis goat mammary gland." (PMID 35498722, 2022). "In this research, results showed the effects of mastitis on the S100A7 expression in the mammary gland and S100A7 concentration in milk and the limited relationship between SCC and mastitis, which provided a new insight into S100A7’s role in the host defenses of dairy goats." (PMID 37999476, 2023). "The S100A7 concentration in milk has a limited relationship with SCC or mastitis." (PMID 37999476, 2023). "In a word, S100A7 plays a potential role in the innate immune system of the mammary gland, yet the relationship between mastitis and S100A7 expression in dairy goats is still unknown." (PMID 37999476, 2023).
mastitis (continued). "Studies show that the expression level of antibacterial peptide S100A7 mRNA in the mammary cells of goats has a good correlation with mastitis, which could reflect the severity of mastitis in a certain range." (PMID 37760235, 2023). "S100A7 shows antimicrobial activity against E. coli; therefore, treatment could contribute to preventing E. coli-induced mastitis." (PMID 36801983, 2023). "In order to verify this hypothesis, the expression of CNP, NPR-B, and S100A7 in healthy (n = 6) and mastitis (n = 6) goats was detected by immunohistochemistry and quantitative PCR." (PMID 35498722, 2022). "CNP/NPR-B, which induced goat MECs to express and secrete S100A7, may be involved in the occurrence or prevention of mastitis in goat." (PMID 35498722, 2022). "In summary, both antimicrobial peptide S100A7 and estrogen abundance were detected in dairy goat milk; their abundances had a limited significance in healthy and mastitis goat milk, and their relationship was positive; the regression equation was y = 0.3206x + 23.459." (PMID 36428305, 2022). "The immunohistochemical results showed that the densely NPR-B and S100A7 immunoreactivity could be observed in collapsed alveolus in mastitis mammary gland." (PMID 35498722, 2022). "Similarly, the mRNAs of NPR-B and S100A7 in mastitis goat mammary gland tissues were apparently upregulated compared to that in healthy goat (p < 0.01)." (PMID 35498722, 2022). "Moreover, S100A7 expression increased significantly in mastitis goats than in healthy dairy goats." (PMID 37999476, 2023). "S100A7 is localized in the epithelial cells and forms homodimers by non-covalent bindings and is also found in bovine and goat, yet the research about the effect of mastitis on its expression in small ruminants remains unclear." (PMID 37999476, 2023). "However, the S100A7 immunoreactivity could be observed densely in the collapsed alveolus of the clinical mastitis goat mammary gland." (PMID 37999476, 2023). "Therefore, it is a hypothesis that CNP/NPR-B, which induced goat MECs to express and secrete S100A7, may be involved in the occurrence or prevention of mastitis in goat." (PMID 35498722, 2022). "Interestingly, S100A7 concentration was significantly higher in subclinical mastitis, while it was slightly upregulated in clinical mastitis goats, which may reduce the breakdown of alveolus function in clinical goats that disordered the source of S100A7." (PMID 37999476, 2023). "The S100A7 concentration in milk has a limited relationship with SCC or mastitis, which show the limited monitoring for mastitis in dairy goat." (PMID 37999476, 2023). "S100A7 plays an essential role in goat mammary glands for a broad spectrum of resisting the invasion and infection of pathogenic microorganisms, and also is considered an alternative strategy for preventing and treating mastitis to broad-spectrum antibacterial strategies, with almost no resistance." (PMID 36428305, 2022). "In subclinical mastitis goats, the AUC of log10 SCC was 0.9222, p < 0.0001, and the AUC of S100A7 concentration was 0.7317, p = 0.0022; in clinical mastitis goats, the AUC of log10 SCC was 0.9678, p < 0.0001, and the AUC of S100A7 concentration was 0.5487, p = 0.5634." (PMID 37999476, 2023). "During mastitis, inflammatory cells such as monocytes, neutrophils, T cells, and macrophages invade into alveolus and expressed CNP to induce the expression and secretion of S100A7 from MECs." (PMID 35498722, 2022).
COVID-19 (4 papers, 2021 to 2024). A disease caused by infection with severe acute respiratory syndrome coronavirus 2. "However, in this study, an upregulation of other pro-inflammatory cytokines, including CRNN, IL1A, IL23A, IVL, and S100A7, was associated with severe COVID-19." (PMID 38375062, 2024). "Taken together, we found that COVID-19 severity in the Ghanaian cohort was associated with dysregulated inflammatory response mediated by MAL, IL1A, IL23A, CRNN, and S100A7 overexpression and suppression of antiviral immune response-related pathways." (PMID 38375062, 2024). "COVID-19 severity was associated with immune suppression, overexpression of proinflammatory cytokines, including CRNN, IL1A, S100A7, and IL23A, and activation of pathways involved in keratinocyte proliferation." (PMID 38375062, 2024). "Finally, we demonstrated that influenza virus infection also induces the expression of S100A7, S100A8, S100A9, and S100A12 in the alveolus chip, a finding that is consistent with recent clinical observations from COVID-19 patients that exhibit late stage lung infections with SARS-CoV-2 virus." (PMID 35396513, 2022).
head and neck squamous cell carcinoma (4 papers, 2010 to 2024). A squamous cell carcinoma that arises from any of the following anatomic sites: lip and oral cavity, nasal cavity, paranasal sinuses, pharynx, larynx, and salivary glands. "S100A7 expression was associated with the expression of DNA methyltransferase and mismatch repair genes in head and neck squamous cell carcinoma, the infiltration of CD8+ T cells and cancer-associated fibroblasts in different tumors." (PMID 35205150, 2022). "Tissue proteomic analysis of head and neck squamous cell carcinoma (HNSCC) and normal oral mucosa using iTRAQ (isobaric tag for relative and absolute quantitation) labeling and liquid chromatography-mass spectrometry, led to the identification of a panel of biomarkers including S100A7." (PMID 20689826, 2010).
metastatic melanoma (4 papers, 2010 to 2024). A melanoma that has spread from its primary site to another anatomic site. "Analysis of publicly available gene expression profiles showed that S100A7 was highly expressed in primary cutaneous melanoma, but was significantly decreased in normal skin tissue and metastatic melanoma." (PMID 36553569, 2022).
oral squamous cell carcinoma (4 papers, 2017 to 2024). "Trials using a non-invasive approach to examine salivary samples of patients with oral squamous cell carcinoma (OSCC) reported S100A7 overexpression, indicating that salivary S100A7 levels may assist in detecting early stages of this disease." (PMID 32334479, 2020). "Similar to the role of S100A7 in oral squamous cell carcinomas (OSCC), with high expression in pre-invasive, well-differentiated and early-stage oral squamous cell carcinomas, but not in non-invasive, poorly differentiated, late-stage tumors." (PMID 28212564, 2017).
systemic sclerosis (4 papers, 2016 to 2023). A chronic disorder, possibly autoimmune, marked by excessive production of collagen which results in hardening and thickening of body tissues. "Of these, S100-A7 is abundant in the saliva of patients with systemic sclerosis and has recently been reported to act as an antimicrobial peptide." (PMID 36894881, 2023). "S100A7 levels correlate with lung involvement in systemic sclerosis, and the increased expression of psoriasin in the whole saliva has a specificity of 50% and a sensitivity of 85% in detecting lung involvement in this condition." (PMID 34239729, 2021). "Infact, among S100 A proteins, S100A7, S100A8, S100A9, S100A12 have been already described as differentially expressed in other systemic autoimmune diseases and particularly in Systemic Sclerosis." (PMID 31249499, 2019).
trachoma (4 papers, 2012 to 2020). "This may be of relevance to trachoma, as Th1 responses (characterized by increased IFNγ) are thought to be associated with a less scarred outcome, which could conceivably be partly mediated through suppression of S100A7." (PMID 23285311, 2012). "We have also found S100A7 expression to be significantly increased in children with signs of clinically active trachoma." (PMID 23285311, 2012). "In the light of new information becoming available about the contribution of S100A7 to other diseases, our findings suggest that this molecule warrants further investigation in trachoma." (PMID 23285311, 2012). "S100A7 appears to mediates these effects through increasing inflammation and activation of MMPs, which have parallels in trachoma." (PMID 23285311, 2012). "S100A7 is able to promote inflammation and may contribute to the development of the scarring process in trachoma." (PMID 23285311, 2012).